CD4 (CD4 molecule)
Diseases named in the same sentence as CD4 in open-access papers (continued):
Sharing a sentence is not in itself a finding about the gene and the disease.
diabetes (continued). "In the current study, we have found a correlation between low percentages of Foxp3-expressing CD4+ Tregs in NOD mice and the high incidence of diabetes (90-100%) in our colony." (PMID 31281853, 2019). "However, using a CD4+ T cell-mediated adoptive transfer model of autoimmune diabetes we observed that even though diabetes does not develop in Ifnγr2-deficient recipient mice, IFNγ-induced MHC class II on IECs is not important for development of insulitis or diabetes." (PMID 30555479, 2018). "After allowing eight weeks for reconstitution, mice were injected with 5 × 105 sorted CD4+ BDC2.5high CD25− T cells, and diabetes monitored." (PMID 30555479, 2018). "Our study also showed that the exogenous IL-33 leads to the expansion of CD11c+IL-2+ cells and increased number of CD4+Foxp3+ST2+ immunoregulatory cells that suppress the development of diabetes in mice treated with IL-33 during the induction of the disease." (PMID 30498495, 2018). "Factors associated with LF at multivariate analysis included: age, HCV infection, nadir CD4, HIV-RNA viral load>100,000 copie/mL, diabetes, exposure to ART." (PMID 29324755, 2018). "A similar study showed at both 1 and 8 months post diabetes induction (STZ) in rats, there was an increased infiltration of CD4+ T cells, CD8+ T cells, and macrophages into the glomeruli." (PMID 29910771, 2018). "Consistently, a delayed development of diabetes was seen in B7-2 knockout NOD mice, where islet-reactive CD4 T cells were defective." (PMID 29416823, 2018). "We enrolled 55 participants; median age 51 years (range 23 to 64), 24% female, 82% Black, median time on HD 6 years (range 1 to 17), median CD4 count 515 cells/ml (IQR 387, 672), and 22% Hepatitis C Ab positive, and 27% history of diabetes." (PMID 29671462, 2018). "Moreover, this might lead to the disabilities in initial T-cell priming and proliferation, because T-bet is the critical transcription factor for Th1 polarization in CD4+ T cells, which helps to explain the critical role of Th1 cells in insulitis and diabetes development." (PMID 28420440, 2017). "Several studies have demonstrated the requirement for both CD4 T cells and CD8 T cells in diabetes recurrence in NOD mice." (PMID 29259578, 2017). "On adoptive transfer into InsHA mice, both HA-specific TCR transgenic clone 4 CD8+ and HNT CD4+ T cells (MHC class I or II restricted, respectively) are required to induce diabetes under inflammatory conditions." (PMID 29403481, 2017). "Such information includes reliable data on illicit drug use, cART regimens and adherence, CD4+ cell counts, HIV viral loads, stroke management, and management of comorbidities such as hypertension and diabetes." (PMID 28617855, 2017). "In the ob/ob model of diabetes and NASH, oral administration of Imm124E decreased serum TNF-α levels, and increased the number of splenic CD4+CD25+, CD4+CD25+Foxp3+ Tregs, and NKT cells." (PMID 26900473, 2016). "Risk factors for SBI include low CD4 count and detectable HIV RNA, but also CD4/CD8 ratio, HCV coinfection, history of cancer and diabetes, comorbid conditions that have been frequent among PLHIV in recent years." (PMID 27050752, 2016). "Similarly, the transfer of 3.5 × 105 purified CD25+ CD4+ T cells (containing largely Treg cells) from vaccinated/ppins-primed, but not from non-immunized donor mice into PD-L1−/− hosts one week after the injection of the diabetogenic pCI/ppins DNA efficiently suppressed diabetes induction." (PMID 27406624, 2016). "After the ATS treatment has reduced the levels of both CD4+ and CD8+ T cells, GAD65 primed DN T cells that were converted from CD4+ T cells in vitro were transferred 7 days after diabetes onset." (PMID 26911290, 2016). "The confounders accounted for were age, HIV transmission group, current CD4 T cell count, haemoglobin level, body mass index, smoking status, anti-HCV antibodies positivity, HBs antigen positivity, diabetes and hypertension." (PMID 26200661, 2015).
diabetes (continued). "The results demonstrate the role of both CD4+ and CD8+ T-cells in protection against melioidosis, and an interaction between diabetes and cellular responses." (PMID 26495852, 2015). "The islet reactive transgenic CD4 T cell specificity denoted BDC2.5 has previously been reported and initial characterization demonstrated the development of diabetes in mice expressing this receptor." (PMID 25171173, 2014). "The insulin B9–23 domain, containing both, a dominant CD4 and a Kd-restricted B15–23 CD8 T-cell epitope, plays a prominent role in the diabetes development in NOD mice." (PMID 23977133, 2013). "We observed that vaccination with the N-terminal fragment of RegII (NtfrRII) accelerated diabetes in NOD mice and that CD4+ T-cells from immunized mice transferred the disease to NOD-SCID recipients." (PMID 23894487, 2013). "Treg cells play a protective role in models of both hypertension and diabetes, and the function of CD4+CD25+ Treg cells was impaired in hypertension and diabetes." (PMID 24385687, 2013). "As an example, transgenic expression of an HA-reactive TCR on CD4+ (TCR-HA107–119) or CD8+ (CL4-HA512–520) T cells promotes spontaneous diabetes development in mice that additionally express HA under control of the rat insulin promoter (RIP-HA)." (PMID 23691523, 2013). "To understand the significance of RAGE expression on T cellular function, we studied the phenotype of RAGE+ and RAGE− CD4+ and CD8+ T cells from patients with diabetes." (PMID 22509345, 2012). "Three Japanese patients presenting with diabetes after receipt of HAART have been shown to develop antibodies to glutamic acid decarboxylase, at a time when CD4 counts shot up suddenly." (PMID 21232158, 2011). "For example, similar to the studies by Morel and colleagues, mature DCs were shown to expand CD4+ CD25+ CD4+ Foxp3+ T cells which were functionally suppressive and capable of preventing diabetes in the NOD mouse." (PMID 21785616, 2011). "In summary, this study demonstrates that low doses of orally administered silkworm-produced CTB-Ins-GFP protein can effectively suppress the development of diabetes in NOD mice, where the treatment function involves inducing CD4+CD25+Foxp3+ Treg cells." (PMID 21765853, 2011). "Total splenocytes were harvested from 32-week-old anti-GITRL antibody-treated diabetes-free NOD mice and were depleted of regulatory T cells i.e. CD4+CD25+ T cells and CD4+CD62L+ T cells." (PMID 19936238, 2009). "There is also clinical support for this concept, since insulin-dependent diabetes mellitus (IDDM) patients show significantly reduced Bcl-2 expression in CD3+ and memory CD4+CD45RO+ populations and have higher levels of spontaneous apoptosis." (PMID 18773086, 2008). "After adjusting for age, sex, and comorbidities, a graded increase in mortality risk persisted across most prespecified subgroups (including sex, age, diabetes, antiretroviral therapy (ART) treatment, SOFA score, cirrhosis, septic shock, and PCP), with the high-CD4/low-TYG group as the reference." (PMID 41601726, 2026). "Cases were more likely to inject drugs, have no education beyond mandatory schooling, have underweight BMI, be current smokers, have hypertension, diabetes, chronic HCV infection, detectable HIV-viremia, CD4 < 350, CD4 < 200, CD4 nadir<50, and CDC stage C illness." (PMID 41505443, 2026). "Key risk factors for MRSA colonization include a history of hospitalization (RR: 2.2), prior antibiotic use (RR: 1.4), diabetes mellitus (RR: 4.4), HIV with CD4 < 200 cells/μL (RR: 2.8), invasive procedures (RR: 4.8), and being a nurse compared to a physician (RR: 1.8), all with p < 0.05." (PMID 40217166, 2025). "This investigation analyzed the risk factors for bacterial lung infection in patients with advanced lung adenocarcinoma and found that age, smoking, stage, bronchiectasis, diabetes, CD3+ T cell percentage, and CD4+ T cell count were closely related to bacterial lung infection." (PMID 40308586, 2025).
diabetes (continued). "In those diabetes participants where S‐specific T cells were detected, the response was unfocused, with the expected expression of IFNγ, TNF, and IL‐2, alongside a significant increase in the expression of the Th2 cytokine IL‐13 in S‐specific CD4+ and CD8+ T cells from both diabetes groups." (PMID 41367201, 2025). "The CD4+ T-cell percentage was significantly higher in diabetes-prone NOD mice than in non-diabetes-prone C57BL/6 mice." (PMID 41197380, 2025). "In addition, the administration of vitamin D resulted in a substantial decrease in the numbers of CD4+ and CD8+ cells in the group of individuals with diabetes (p < 0.0001)." (PMID 39812046, 2025). "To further refine our model, we employed LASSO regression analysis, which selected the following variables: CD4 count, Hb, platelet count (PLT), ALB, VD, lumber spine BMD, current smoking status, diabetes, history of falls, TDF usage, and HIV RNA load (1000-100000 copies/mL)." (PMID 40160472, 2025). "This comprehensive approach, supported by existing literature, confirmed that the top 10 most important variables for our final model were: Age, current smoking status, diabetes, history of falls, TDF usage, HIV RNA load, CD4, white blood cell count (WBC), Hb, and lumbar spine BMD." (PMID 40160472, 2025). "In addition to clusters of differentiation 4 (CD4) count and duration and type of HAART, the increment in diabetes among people on ART is due to the same risk factors as the general population who develop type-2 diabetes mellitus (DM)." (PMID 40313886, 2025). "Mice in the diabetes group showed a decrease in naïve CD4+ T cell population, and there was a slight, but not significant, increase in those of effector and memory cells." (PMID 41158127, 2025). "Furthermore, we showed that CX3CR1+ GPR56+ CD57+ (referred to as “CGC+”) CD4+ and CD8+ T cells are cytotoxic and increased in PLWH who also have diabetes and subclinical atherosclerosis." (PMID 41194668, 2025). "Factors significantly associated with MRSA colonization included a history of hospitalization (RR = 2.2, P < 0.001), prior antibiotic use (RR = 1.4, P = 0.001), diabetes mellitus (RR = 4.4, P = 0.015), and HIV-positive status with a CD4 count below 200 cells/μL (RR = 2.8, P = 0.002)." (PMID 40217166, 2025). "Higher treatment failure odds were linked to smear-negative TB, high viral load, and hypertension–diabetes comorbidity, while CD4 count and HIV treatment status showed no independent effects." (PMID 40723967, 2025). "Key risk factors significantly associated with MRSA colonization (p < 0.05) include hospitalization (RR: 2.2), prior antibiotic use (RR: 1.4), diabetes mellitus (RR: 4.4), HIV with CD4 counts below 200 (RR: 2.8), invasive procedures (RR: 4.8), and being a nurse compared to a physician (RR: 1.8)." (PMID 40217166, 2025). "In T2D patients, there were significant clonal expansions observed in cytotoxic T cells (CD4 Tcyt and CD8 Tem), with the clonality size, measured using the Gini index, being notably higher in T2D cytotoxic T cells than in those from the non-diabetes." (PMID 39072276, 2024). "Indeed, the onset of diabetes, specifically T1DM, results from macrophage activation which drives the recruitment of CD8+ and CD4+ T cells to the islet, ultimately resulting in the destruction of β cells." (PMID 39580467, 2024). "CD4+ T cells reactive to ZnT8 are unable to stimulate disease during transfer into NOD or NOD.Rag1-/- mice, and are only found in the pancreas or accelerate diabetes if significant islet damage is already present." (PMID 39211046, 2024). "In addition to increased inflammation, the present study also found that the T cells (CD4+ T lymphocytes, CD8+ T lymphocytes, NK cells, and NKT cells) in patients with diabetes were significantly decreased." (PMID 39026159, 2024).
diabetes (continued). "Interestingly, some studies have reported that patients with type 2 diabetes mellitus (T2DM) show elevated white blood cell counts, yet they are more likely to have decreased lymphocyte counts and an increased presence of senescent CD4+ and CD8+ T cells." (PMID 39202264, 2024). "The upregulation of CD73 with agents, including AGT-5, Aire-overexpressing DCs, Aspirin, BAFFR-Fc, CD4+ peptide, ICAs, IL-2 therapies, SAgAs, sCD73, stem cells, RAD51 inhibitor, TLR9 inhibitor, and VD, decreased the development of diabetes and atherosclerosis in preclinical trials." (PMID 39735551, 2024). "Additionally, both diabetes mellitus and programmed cell death protein 1 (PD-1) expression on CD3+/CD4+ T cells negatively impacted TNF-α levels, while body mass index was inversely associated with IFN-γ production." (PMID 39456722, 2024). "Overall, the relationship between CD4+ cells and IgM or IgG status was not influenced by patients’ characteristics, with the exception of symptomatology and diabetes." (PMID 38346064, 2024). "Of the 1499 assessable participants included in the primary analysis, 686 (45·8%) were female, 813 (54·2%) were male, the median age was 41·0 years (IQR 29·0–54·0), 229 (15·3%) were living with HIV (median CD4 count 399 cells per μL [IQR 206–667]), and 202 (13·5%) had diabetes (HbA1c ≥6·5%)." (PMID 38245113, 2024). "Potentially useful variables such as CD4 counts, TB diagnostics or treatment used, nutritional status, income, quantification of alcohol intake, diabetes control, and other socioeconomic determinants were not included to keep the CRF brief." (PMID 39131588, 2024). "This review, comprising cross‐sectional studies, highlights the lack of associations between diabetes and HIV‐related factors of CD4 count, ART use and duration of ART use." (PMID 36924213, 2023). "Diabetes prevalence was also not significantly different by HIV‐related factors of CD4 count, ART use or duration of ART use." (PMID 36924213, 2023). "Persons with diabetes had substantially greater CD4 counts at diagnosis than persons without diabetes." (PMID 37442942, 2023). "In this setting, diabetes, Hispanic ethnicity and nadir CD4+ T cell counts, but not NAFLD or clinically significant fibrosis, were associated with impaired HRQOL in PWH." (PMID 36763643, 2023). "The results suggest the frequencies of differentiated and senescent CD4+ and CD8+ lymphocyte subsets in peripheral blood are not strongly associated with the risk of incident diabetes in older adults free of autoimmune disease." (PMID 36333945, 2023). "Low-impact voluntary exercise did not increase low CD4+ T helper cell counts in patients with diabetes." (PMID 37109747, 2023). "In summary, diabetes, non-Hispanic ethnicity, and nadir CD4+ T cell counts, but not NAFLD or clinically significant fibrosis, were associated with impaired HRQOL in PWH on ART achieving adequate HIV viral suppression." (PMID 36763643, 2023). "Similar to our analyses, these studies adjusted their outcome for baseline participant characteristics, such as country of origin, socioeconomic status, current CD4+ cell count and CD4/CD8 ratio, years on ART, presence of diabetes, chronic kidney disease, and metabolic disease." (PMID 37395254, 2023). "Diabetes may increase the severity of SARS-CoV-2 infection because of lower levels of CD8+ T cells and higher levels of CD4+ T cells, specifically an imbalance ratio of Th1/Th2 cells." (PMID 36839596, 2023). "None of the Cp-treated mice developed diabetes suggesting that Cp inhibited the CD4+ T-cell infiltration of the pancreatic islets and promoted an anti-inflammatory response that preserved the integrity of this organ." (PMID 37242733, 2023). "Using the cut off of 13.4%, we assessed whether the number of affected systems differed between patients who presented with diabetes and had %TSDR/CD4 values above or below the threshold." (PMID 36600150, 2023).
diabetes (continued). "The role of Tregs was even more apparent on day 14 post-immunization, which corresponded to the typical onset of diabetes in the absence of conventional CD4+ T cells." (PMID 36705564, 2023). "Participants who were overweight or obese (AOR: 2.15, 95%CI: 1.18 – 2.54), had diabetes mellitus (AOR: 2.63, 95%CI: 1.38 – 5.03), renal disease (AOR: 4.21, 95%CI: 1.04 – 16.98) and CD4 counts ≥ 201cells/μL (AOR: 1.21, 95%CI: 1.03 – 1.44) were more likely to have hypertension." (PMID 37908015, 2023). "Participants who were overweight or obese (AOR: 2.18, 95%CI: 1.85 – 2.57), had diabetes mellitus (AOR: 2.59, 95%CI: 1.37 – 4.93), renal disease (AOR: 4.20, 95%CI: 1.04 – 16.89) and CD4 counts ≥ 201cells/μL (AOR: 1.23, 95%CI: 1.05 – 2.57) were more likely to have hypertension." (PMID 37908015, 2023). "In patients with type 2 diabetes, kallikrein-related peptidase 5, an enzyme responsible for the shedding of DPP4 from cell membrane, was induced in CD4+ T cells, suggesting that immune cell-derived DPP4 is responsible for reduced incretin effect in diabetes patients." (PMID 35309368, 2022). "At univariate analysis, BNP, β2-MG, cFLCs, and sHMGB1 were significantly associated with the endpoint, whereas diabetes, ferritin, CRP, CD4+/CD8+ ratio, and age failed to reach statistical significance." (PMID 36498479, 2022). "In patients with diabetes (T1D, LADA, and T2D as a combined group), 1) IFN-γ+CD4+ T and IFN-γ+CD8+ T cells were positively correlated with age, 2) Th2 cells were negatively correlated with disease duration, and 3) Th17 cells were positively correlated with blood glucose." (PMID 36091068, 2022). "Although HPSE-1 from antigen-specific CD4+ T cells is clearly involved in diabetes initiation, it did not attain the diabetes incidence observed in WT controls." (PMID 35563015, 2022). "Moreover, Tlr7−/− NOD B cells were found to suppress diabetogenic CD4+ T-cell responses and protect immunodeficient NOD mice from developing diabetes induced by diabetogenic T cells." (PMID 33432061, 2021). "Both CD4+ and CD8+ T cells are important for the progression of diabetes in mice and humans." (PMID 34433860, 2021). "Available data included date of birth, gender, ethnicity, lymphocyte T CD4+ count, weight, height, blood pressure, current/ex/non-smoker, diabetes mellitus, familial cardiovascular event, lipid profile, duration and nature of antiretroviral therapy." (PMID 34488664, 2021). "2.5 x106 murine CD4+ Insulin-CAR-FOXP3-T cells failed to prevent the onset of diabetes in prediabetic NOD mice." (PMID 33854514, 2021). "This interpretation is further supported by our observation that, in contrast to anti-CD4 mAb, anti-CD8 and anti-CD3 mAb administration into DT-treated NOD.DEREG mice interfered with the progression to overt diabetes, despite substantial histopathological changes." (PMID 34447385, 2021). "After transplanting SA‐FasL engineered islets into diabetic allogeneic hosts in conjunction with a short‐term course (14 days post‐transplantation) of rapamycin treatment, robust localized tolerance was induced by CD4+CD25+Foxp3+ regulatory T (Treg) cells and the reversal of diabetes was noted." (PMID 34258870, 2021). "Although the mechanisms stimulating the change of the immune responses are diverse, and are not fully understood yet, targeting effector CD4+ T cells and CD8+ T cells, key mediators of β cell damage, has been the focus of immunotherapeutic approaches to prevent diabetes." (PMID 34484126, 2021). "Diabetes promoted B cell activation and upregulated the expression of CD80 and CD86, which may account for the differentiation of CD4+ T cells from Treg cells towards Th1/Th17 cells." (PMID 34702288, 2021). "Despite the rapid development of overt diabetes, the number of splenic, PLN, and pancreas-infiltrating CD4+ T cells was reduced in BDC.Foxo1–/– mice approximately 10-fold compared with BDC.Foxo1+/+ mice, which is consistent with reduced peripheral T cell numbers in Foxo1-deficent mice." (PMID 34314385, 2021).